PARP1 (poly(ADP-ribose) polymerase 1)
Diseases named in the same sentence as PARP1 in open-access papers (continued):
Sharing a sentence is not in itself a finding about the gene and the disease.
asthma (continued). "Overall, our results show that PARP-1 plays little to no role in DC differentiation and function and that the protective effect of PARP-1 inhibition against asthma is associated with a prevention of DC migration to the lung through a reduction in VCAM-1 expression." (PMID 31178661, 2019). "Despite the fact that PARP-1 has been reported to play a role in AP-1 activation in several inflammatory disorders, including ALI, we could not find any study in literature addressing the PARP and AP-1 interrelationship in asthma." (PMID 28974953, 2017). "To test the role of PARP-1 in CD4+ T cell function during an allergic response, we examined whether adoptive transfer of WT CD4+ T cells isolated from OT-II mice that were skewed in vitro toward a Th2 phenotype reverses asthma-like traits in naïve PARP-1−/− mice upon OVA exposure." (PMID 26169874, 2015). "It is important to acknowledge that the study, as conducted, does not cover all the aspects of asthma manifestation and it remains to be determined whether the transfer of WT CD4+ T cells is sufficient to reverse AHR and mucus production in PARP-1−/− mice." (PMID 26169874, 2015).
lymphoma (22 papers, 2009 to 2025). A malignant (clonal) proliferation of B- lymphocytes or T- lymphocytes which involves the lymph nodes, bone marrow and/or extranodal sites. "This contrasting effect of PARP1 deficiency (accelerating lymphoma) versus its prosurvival role in solid tumors highlights the tissue and context specificity of PARP1 function." (PMID 40904702, 2025). "In B‐cell lymphoma, PARP1 deficiency → ↑proinflammatory response and Treg cell accumulation → accelerates c‐Myc‐driven lymphoma progression." (PMID 40904702, 2025). "In an Em‐Myc mouse model, PARP1 deficiency accelerated lymphoma development." (PMID 40904702, 2025). "And the STAT3 (rs744166), IL2 (rs2069762), IL10 (rs1800871), and PARP1 (rs907187) manifested a significant relationship with the peripheral blood counts in lymphoma patients." (PMID 37329186, 2023). "Consistent with our previous findings from murine lymphoma cells, we also detected PARP-1 cleavage 24 h after treatment with M-100." (PMID 36068335, 2022). "Phenformin treatment also increased apoptosis in the lymphoma cells as shown by a large increase in cleaved PARP1, although only when AMPK was present." (PMID 30995468, 2019). "Parp1 was first identified in malignant lymphoma to enhance the expression of poly(ADP-ribose) synthetase gene as well as the expressions of proto-oncogenes such as c-myc, c-fos, and c-myb." (PMID 26184161, 2015). "Chemotherapy induced dose-dependent caspase-3 activation and PARP-1 cleavage in tumors of EL4 lymphoma-bearing mice." (PMID 19247492, 2009). "Besides, Parp-1 cleavage was detected in M-100-treated mouse lymphoma cells, indicating apoptosis induction." (PMID 36068335, 2022). "Combination of HDAC and PARP1 inhibitors provided synergistic cytotoxicity, which was further enhanced when combined with a chemotherapeutic regimen containing gemcitabine, busulfan and melphalan as observed in lymphoma cell lines." (PMID 36243940, 2022). "In an early study, Parp1 was identified in lymphoma cell line with enhanced expression level." (PMID 26184161, 2015). "For instance, in the chicken lymphoma DT40 cell line, talazoparib was found to be 100‐fold more potent in PARP‐1 ‘trapping’ than rucaparib and olaparib, because rucaparib and olaparib were not effective ‘trappers’." (PMID 41230800, 2025). "DTX3L is reported to regulate the ubiquitin modification of PARP family proteins (PARP1, PARP2, PARP9, PARP14), promoting proliferation, migration and chemotherapy resistance of lymphoma, glioma, and melanoma." (PMID 38304253, 2023).
Obesity (22 papers, 2008 to 2026). Accumulation of substantial excess body fat. "Our studies demonstrate that the increased propensity to obesity in Ogg1−/− mice is associated with reductions in PARP1 activity, while obesity resistance in Ogg1Tg animals is associated with increased cellular PARylation." (PMID 33503804, 2021). "By contrast, PARP1−/− mice in the 129/Sv background were susceptible to obesity, especially at older ages, and also prone to diet-induced obesity." (PMID 31842403, 2019). "For instance, in two different studies investigating the effect of PARP1 deficiency on metabolism and obesity, different results emanated from distinct mouse genetic backgrounds." (PMID 31842403, 2019). "On the other hand, PARP1 inhibition and deletion in mice were associated with improvement of diabetes- or obesity-related parameters such as glucose tolerance, weight loss, or fat mass reduction (reviewed in Bai and Cantó, 2012)." (PMID 30356649, 2018). "PARP-1−/− mice with predominantly obesity-resistant backgrounds were more susceptible to age-related weight gain and diet-induced obesity than wild-type littermates, while the decreased activity of PARP-1 in mice with obesity-prone background protected against high-fat diet-induced obesity." (PMID 23800102, 2013). "We investigated Caspase-3 and PARP-1 activation and degradation upon exposure to chemotherapeutic drugs under the obesity micro-environment." (PMID 38247865, 2024). "TNF-α downregulated some of the DNA damage repair genes, which are also altered by obesity: PARP1 (−49.3%, P = 0.008), BLM (−46.9%, P = 0.02), FEN1 (−25.5%, P = 0.04), and PCNA (−38.0%, P = 0.008), but did not affect HDAC1 and Ku70 gene expression." (PMID 39092995, 2024). "Recent studies have demonstrated that poly(ADP-ribosyl)ation (PARylation) of cellular proteins inhibits adipogenesis, and a whole-body knockout model of PARP1 was shown to develop obesity and increased adiposity, similar to the Ogg1−/− mouse." (PMID 33503804, 2021). "PARP1 gene deletion and inhibition have been reported to enhance lipid accumulation in the liver and exacerbate high-fat-induced obesity in mice." (PMID 33208446, 2021). "Similar to the ambiguity in the role of PARP1 in adipocyte differentiation, the studies on the organismal role of PARP1 in obesity and its consequences are also contradictory." (PMID 32029456, 2020). "Disruption of circadian entrainment of feeding can also contribute to obesity and the disruption of PARP1 leads to changes in the diurnal cycle of feeding and metabolism." (PMID 32029456, 2020). "Furthermore, PARP1 expression was increased in explants from cancer patients when compared to lean participants and those with obesity (p < 0.05)." (PMID 36982562, 2023). "We identified an increased risk of hepatic dysfunction by biogenic amine ingestion in obesity and confirmed that both blood and liver biomarkers, including CRP, MAO, IL-1β, and PARP-1, are helpful markers for evaluating hepatic function in biogenic amine-induced liver damage in obesity." (PMID 36899958, 2023). "Two different models of whole body PARP1 deletion reported opposing results regarding either protection from or exacerbation of obesity as a consequence of PARP1 deletion, while a more recent report indicated that PARP1 ablation only in preadipocytes resulted in the development of obesity." (PMID 33503804, 2021). "Similarly, other studies have also established the regulation of PARP-1 in several disease conditions, including hypertension, obesity, and inflammation." (PMID 34698261, 2021). "Therefore, the role of PARP1 in lipid metabolism remains inconclusive, at least in the context of the liver and diet-induced obesity." (PMID 33208446, 2021). "On the one hand, mice lacking PARP1 displayed aberrant circadian rhythms and diet-induced obesity associated with hepatic steatosis." (PMID 30356649, 2018).
Obesity (continued). "PARP-1 is a critical regulator of peroxisome proliferator-activated receptor gamma (PPARγ2)-dependent gene expression with implications in adipocyte function and obesity-related disease models." (PMID 23800102, 2013). "Our study shed new insight into the observed obesity-EC associations: it is proposed that obesity may be an epiphenomenon underlying abnormal PARP1 metabolism rather than the direct cause of the EC." (PMID 23762867, 2013). "However, these animals are susceptible to developing epidermal hyperplasia and obesity at older ages and cells lacking PARP1 are susceptible to genotoxic stress." (PMID 21124852, 2010). "For example, PARP1/2 knockout enhances SIRT1 activity leading to increased mitochondrial function, fatty acid oxidation and protection against obesity." (PMID 32423100, 2020). "In murine studies, PARP1, PARP2, and tankyrase-1 were shown to be involved in modulating energy balance and obesity." (PMID 32029456, 2020). "It has been well demonstrated that the protein expression of NAMPT is decreased, while the level of PARP1 is increased during HFD feeding and obesity, which leads to NAD+ depletion." (PMID 28786950, 2017). "It is well established that metabolic stresses, including obesity, type 2 diabetes, smoking, heart failure, hypertension, nerve damage, and brain injury, deplete intracellular ATP and NAD+ in affected tissues with a dramatic induction of ROS and PARP-1 expression." (PMID 34698261, 2021).
Sepsis (22 papers, 2012 to 2026). Sepsis is defined as life-threatening organ dysfunction caused by a dysregulated host response to infection. "Sepsis and other forms of critical illness are closely associated with PARP1 activation." (PMID 35740913, 2022). "Because PARP1 also directly contributes to cell death in affected tissues it is hypothesized that PARP1 has a role in sepsis-associated immune cell death." (PMID 29163354, 2017). "Knocking out PARP1 abolishes the ameliorative effect of specific intervention on liver injury in sepsis." (PMID 40643532, 2025). "Among these, four pathways—disulfidptosis, entotic cell death, ferroptosis, and NETosis—were upregulated in sepsis, while parthanatos (PARP-1-dependent cell death) showed reduced activity." (PMID 41346577, 2025). "circR-TLK1 sponges miR-17-5p to aggravate mtDNA oxidative damage, mitochondrial dysfunction and cardiomyocyte apoptosis via activating PARP1/HMGB1 axis during sepsis." (PMID 35720285, 2022). "Our findings provide evidence that targeting circTLK1/miR‐17‐5p/PARP1/HMGB1 axis confers an effective protection against sepsis‐induced myocardial injury." (PMID 34410682, 2021). "According to our results, sepsis‐induced myocardial apoptosis was significantly repressed by inhibition of circTLK1 or PARP1." (PMID 34410682, 2021). "CircTLK1 sponged miR‐17‐5p to facilitate oxidative stress–mediated mtDNA damage, mitochondrial dysfunction and subsequent apoptosis in sepsis‐induced cardiomyopathy in vitro and in vivo via activating PARP1/HMGB1 axis." (PMID 34410682, 2021). "As detected by TUNEL, sepsis‐induced apoptosis in myocardial tissues was attenuated by circTLK1 down‐regulation, which was further inhibited in the co‐treatment with PARP1 inhibitor and sh‐circTLK1." (PMID 34410682, 2021). "PARP1 is involved in sensing DNA damage and promoting cell survival, but when DNA damage is beyond repair, PARP1 hyper-activates, as during ischemia-reperfusion damage, severe oxidative stress or sepsis." (PMID 27669412, 2016). "Parp1 may also contribute to the inflammatory response and the cellular metabolic disorders in sepsis." (PMID 36766707, 2023). "Notably, we have previously demonstrated PARP1 activation in myocardial samples from patients with sepsis, with a significant correlation with the degree of cardiac dysfunction, and in the skeletal muscle of pediatric patients with burn injury." (PMID 35740913, 2022). "Moreover, circTLK1 knockdown repressed sepsis‐induced mtDNA oxidative damage, mitochondrial dysfunction and consequent cardiomyocyte apoptosis by inhibiting PARP1/HMGB1 axis in vitro and in vivo." (PMID 34410682, 2021). "Thus, circTLK1 inhibition improved sepsis‐induced oxidative stress damage and mitochondrial dysfunction by inhibiting PARP1/HMGB1 axis." (PMID 34410682, 2021). "CircTLK1 sponged miR‐17‐5p to aggravate mtDNA oxidative damage, mitochondrial dysfunction and cardiomyocyte apoptosis via activating PARP1/HMGB1 axis during sepsis, indicating that circTLK1 may be a putative therapeutic target for septic cardiomyopathy." (PMID 34410682, 2021). "Silencing of circTLK1/PARP1 axis could effectively relieve myocardial mtDNA damage during sepsis." (PMID 34410682, 2021). "Interestingly, PARP1 has been demonstrated to promote the secretion of HMGB1 in sepsis." (PMID 34410682, 2021). "Although hyperactivation of poly (ADP-ribose) polymerase-1 (PARP-1) is recognized as a key contributor to inflammation and cellular injury, its cell type-specific roles in sepsis and strategies for targeted inhibition remain insufficiently explored." (PMID 41809387, 2026). "In the LPS-induced sepsis model, the excessive activation of poly (ADP-ribose) polymerase 1 (PARP1) in macrophages is a key factor driving the inflammatory response." (PMID 40643532, 2025).
Sepsis (continued). "Studies have shown that IGFBP7 is important for clinical staging of sepsis-related acute kidney injury because IGFBP7 can delay the progression of acute kidney injury by inhibiting RNF4/PARP1-mediated tubular injury." (PMID 38259686, 2023). "Prior studies demonstrate the activation of poly-(ADP-ribose) polymerase 1 (PARP1) in various pathophysiological conditions, including sepsis." (PMID 35740913, 2022). "Similar to the LPS-mediated sepsis model, PARP1−/− mice were protected from ulcerative colitis induced by trinitrobenzene sulfonic acid (TNBS) treatment, because PARP1 can activate c-Jun of the AP-1 transcription factor." (PMID 36077699, 2022). "PJ-34, a PARP-1 inhibitor, may exert its protective effect on intestinal epithelial cells against invasive Salmonella infection by up-regulating IL-6 production, which has anti-inflammatory and cell-protective effects, and counteracts some of the injurious effects of sepsis and endotoxemia." (PMID 34943999, 2021). "CircTLK1 can sponge miR-17-5p, activate the poly(ADP-ribose) polymerase 1 (PARP1)/HMGB1 axis, and aggravate the oxidative damage of mitochondrial genome (mtDNA), resulting in mitochondrial dysfunction and cardiomyocyte apoptosis in sepsis." (PMID 40041174, 2025). "Inhibitors of PARP1 have been assessed in clinical trials as potential cancer therapeutics, but trials in sepsis and T2D have not been initiated." (PMID 29163354, 2017). "Mechanistically, pimpinellin enhances the ubiquitination-mediated degradation of PARP1, blocks the parthanatos cell death pathway, and restores mitochondrial function, providing a new intervention target of the “RNF146/PARP1 ubiquitination axis” for the treatment of liver injury in sepsis." (PMID 40643532, 2025). "It is not clear whether inhibition of PARP1 in humans would be beneficial in the case of T2D or sepsis." (PMID 29163354, 2017).
bladder cancer (21 papers, 2015 to 2025). "We found regorafenib significantly induces apoptosis and increases activation of Fas/FasL, Caspase‐8, ‐3, loss of ΔΨm, and cleavage of PARP1 in bladder cancer TSGH 8301 cells." (PMID 30801954, 2019). "Furthermore, some of our target genes with low mutation rates (HDAC1 and PARP1) are actually in clinical trials for bladder cancer." (PMID 35035776, 2022). "We generated a PARP1 knockout (PARP1-KO) T24 bladder cancer cells using the CRISPR-based gene-knockout strategy." (PMID 36512630, 2022). "The present data demonstrate the involvement of both intrinsic and extrinsic caspase pathways of apoptosis, which were associated with PARP-1 cleavage, Bax, and Fas induction, and Bcl-2 and XIAP suppression in a MSSV-treated bladder cancer cells." (PMID 33430488, 2021). "Most importantly, preclinical studies indicate that the attenuation of CCDC6 in lung, pleural, prostate and bladder cancer determines cells sensitivity to inhibitors of PARP1/2 enzymes." (PMID 34841108, 2021). "While PARP1 transcription has been reported to be repressed by E2Fs complex in human monocytes, in hypoxic cancer cells, and in bladder cancer." (PMID 31391118, 2019). "Our study demonstrated that hnRNP-L down-regulation resulted in the apoptosis of bladder cancer cells due to activation of apoptosis inducing factors, caspase-3/6/9 and suppression of apoptosis inhibitory factors, Bcl-2, Bcl-xL and PARP1." (PMID 28088793, 2017). "The siRNA reduction of ILK expression had significant effects on PARP-1 protein levels in the bladder cancer cell line T24." (PMID 27683053, 2016). "Western blot analysis demonstrates that BIX-01294 (0, 5, 10 μmol/l) significantly activated CASP8, CASP9, CASP3 and cleaved the substrate of CASP3, PARP1 in bladder cancer cells treated for 24 hours." (PMID 25685062, 2015). "Moreover, preclinical studies indicates that the attenuation of CCDC6 in lung, pleural, prostate and bladder cancer cells confer sensitivity to inhibitors of PARP1/2." (PMID 34841108, 2021). "Furthermore, regorafenib not only enhanced extrinsic and intrinsic apoptosis of bladder cancer cells but also induced the cleavage of PARP1, which also demonstrated as an apoptosis marker." (PMID 30801954, 2019). "As was demonstrated for bladder cancer, tumor cells with low KMT2C activity experienced a deficiency of DNA repair mediated by homologous recombination and suffer from endogenous DNA damage and genomic instability, and their treatment with the PARP1/2 inhibitor olaparib leads to synthetic lethality." (PMID 34572812, 2021). "It downregulated KAT8 and H4K16ac levels in T24 bladder cancer cells, upregulated cleaved poly(ADP-ribose) polymerase 1 (PARP1), downregulated BCL2, and promoted apoptosis." (PMID 40508066, 2025). "Data identified that in the low HER2 cohort and different ATM levels (high/low); ABL1, SMAD4, RB1 and PARP1 were significantly upregulated and AKT1, AKT2, TSC2, RPTOR and mTOR were significantly downregulated in bladder cancer." (PMID 36056635, 2022). "Hence, we provide a novel biomarker candidate, i.e., RBBP8, which has previously been shown to sensitize tumor cells for PARP1 inhibitors and which may improve entity-specificity for monitoring, early detection, and clinical management of bladder cancer in a urine biomarker panel." (PMID 29445424, 2018). "Similar results were also found in HLTF-KO and PARP1-KO HONE6 and bladder cancer T24 cells." (PMID 33281189, 2020). "The data are compatible with a direct function of PARP-1 affecting mitochondria of bladder cancer cells though this was not studied in greater detail." (PMID 30460326, 2018).